TTF1 (transcription termination factor 1)
Diseases named in the same sentence as TTF1 in open-access papers (continued):
Sharing a sentence is not in itself a finding about the gene and the disease.
mucinous lung adenocarcinomas (5 papers, 2018 to 2025). "Knockdown of anti-mucous transcription factor, NKX2-1 (also known as TTF1) in KrasG12D induces mucinous adenocarcinoma of the lung in a murine model." (PMID 36860703, 2022). "Thyroid transcription factor (TTF1) is a marker of lung and thyroid origin, and is expressed in 80% of primary non-mucinous lung adenocarcinomas." (PMID 29881714, 2018). "Vice versa, enteric type and mucinous lung adenocarcinomas frequently show expression of CDX2 and CK20, often also without TTF-1 and Napsin A expression." (PMID 40564811, 2025).
sarcoma (5 papers, 2014 to 2025). A usually aggressive malignant neoplasm of the soft tissue or bone. "Consistently, IHC negative for CK20, CDx2, TTF-1, CD10 and Vimentin excluded urothelial, gastrointestinal, lung, thyroid, kidney cancer and sarcoma metastasis." (PMID 33912469, 2021).
sarcomatoid carcinoma (5 papers, 2019 to 2026). A malignant epithelial neoplasm characterized by the presence of spindle cells and anaplastic morphologic features. "All tumors were adenocarcinomas except one, which was a sarcomatoid carcinoma with an adenocarcinoma (TTF-1 positive) component." (PMID 33510214, 2021). "Biopsy of the duodenum confirmed a poorly differentiated carcinoma with AE1/AE3 (+), CK7 (+), CK19 (−), CK8/18 (+), hepatocytes (−), epithelial membrane antigen (EMA) (+), TTF‐1 (−), and Ki‐67 (approximately 60%+), indicative of sarcomatoid carcinoma." (PMID 32410331, 2020). "Histology demonstrated spindle‐shaped atypical cells, positive for cytokeratin AE1/AE3 and weakly positive for TTF‐1, but negative for mesothelial markers, consistent with sarcomatoid carcinoma of probable pulmonary origin." (PMID 41503244, 2026).
clear cell carcinoma (4 papers, 2011 to 2021). "Other earlier studies reported TTF1 expression ranging from 2% up to 19% in EEC and 9–23% in serous carcinomas and 7% clear cell carcinoma." (PMID 33670088, 2021). "Negative staining of tumor cells with RCC marker, TTF-1, CA-125, ER, and PR help rule out metastatic clear cell carcinomas originating from the kidney, lung, thyroid, ovary, and breast." (PMID 24955270, 2014). "GATA3 and TTF1 are usually negative in clear cell carcinomas." (PMID 33670088, 2021). "Primary clear cell carcinoma is usually Napsin A and TTF-1 negative." (PMID 27013585, 2016).
emphysema (4 papers, 2014 to 2023). "Our immunostaining results showed that administered ADSCs had become engrafted into the emphysema lung even on day 21 and some of the engrafted ADSCs were positive for alveolar epithelial markers such as TTF-1, SPB, and SPC." (PMID 31281377, 2019). "High levels of SPA, SPC, and TTF1 mRNAs were expressed in samples from group I (control group), but these levels were markedly lower by comparison in the emphysema group (group II) (95% confidence intervals, SPA, −0.23 ~ −0.17; SPC, −0.30 ~ −0.28; TTF1, −0.32 ~ −0.28; P < 0.05)." (PMID 25319435, 2014). "In addition, increased expression of TTF-1/NKX2-1 in alveolar type II cells has been found to induce dose-dependent alterations in alveolar morphology, epithelial cell hyperplasia, emphysema, and pulmonary inflammation." (PMID 36672632, 2023).
Ewing sarcoma (4 papers, 2013 to 2025). A small round cell tumor that lacks morphologic, immunohistochemical, and electron microscopic evidence of neuroectodermal differentiation. "TTF-1-positive Ewing sarcoma may erroneously give rise to the diagnosis of a bone metastasis derived from a small cell NEC of the lung or of another site of origin." (PMID 39377914, 2024).
granular cell tumor (4 papers, 2015 to 2024). An unusual benign or malignant neoplasm characterized by the presence of neoplastic large polygonal cells with granular, eosinophilic cytoplasm which contains abundant lysosomes. "They typically show immunopositivity for the thyroid transcription factor-1 (TTF-1) and include pituicytoma (PC), spindle cell oncocytoma (SCO), granular cell tumor (GCT), and sellar ependymoma (SEP)." (PMID 36799985, 2023).
intrahepatic cholangiocarcinoma (4 papers, 2013 to 2023). A carcinoma that arises from the intrahepatic bile duct epithelium in any site of the intrahepatic biliary tree. "Pathological evaluation of the liver mass was consistent with a moderately differentiated intrahepatic cholangiocarcinoma (CK7+, CK20−, TTF-1−) in the absence of any known risk factors." (PMID 24550739, 2014).
kidney tumor (4 papers, 2015 to 2023). "However, the lack of immunoreactivity of the kidney tumor sample with thyroid transcription factor 1 (TTF-1) and cytokeratin 7 (CK-7) antibodies did not support pulmonary origin." (PMID 31484545, 2019). "The kidney tumor of our patient, although the lack of immunoreactivity for CK-20 and CDX-2 ruled out the possibility of metastasis from intestinal origin, the negative results with TTF-1 and CK-7 was not supportive of pulmonary origin." (PMID 31484545, 2019).
liver cancer (4 papers, 2018 to 2023). An epithelial or non-epithelial malignant neoplasm that arises from the liver. "Interestingly, while TTF1 is not described in any previous sequencing studies of liver cancer, it was altered in all three HCC tumors in this study." (PMID 31796844, 2019).
pneumocytoma (4 papers, 2011 to 2025). "The TTF-1 expression observed in AAs is very important in discriminating AAs from sclerosing hemangiomas." (PMID 21592362, 2011). "Sclerosing hemangiomas are positive for TTF-1, surfactant apoprotein A, and cytokeratin." (PMID 23050181, 2012). "Sclerosing pneumocytoma may resemble PTL but includes solid, sclerotic, and haemorrhagic regions, with stromal cells that are positive for TTF-1 and EMA expression." (PMID 40963578, 2025).
rectal cancer (4 papers, 2017 to 2025). A primary or metastatic malignant neoplasm that affects the rectum. "We report a case of napsin A- and TTF-1-positive metastatic lung cancer originating from rectal cancer." (PMID 29124480, 2017). "We report a patient with a metastatic lung tumor originating from rectal cancer that was positive for both napsin A and TTF-1 expression." (PMID 29124480, 2017). "Two metastases of rectal cancer from the same patient were negative for all four markers (and CK20 and TTF-1 while CK7 was positive)." (PMID 37349623, 2024). "The biopsy from the previous rectal cancer was reviewed, and IHC staining showed positive CK7 while CK20 and TTF-1 were both negative." (PMID 28347348, 2017).
synovial sarcoma (4 papers, 2010 to 2025). "When it is necessary to distinguish MM from pulmonary AC, and when a synovial sarcoma can be ruled out, positive IR for TTF-1 would be useful for a pulmonary carcinoma diagnosis." (PMID 20602796, 2010). "In contrast to biphasic synovial sarcoma, the entrapped alveolar glands show consistent pneumocytic phenotype, which is not the case in synovial sarcoma glands (the latter are CK7+, TLE1+, TTF1-, NapsinA-)." (PMID 32193604, 2020).
thyroid agenesis (4 papers, 2015 to 2021). "“PAX8 gene” mutation has been found to be associated with various forms of thyroid dysgenesis, whereas TTF-1 gene mutation has been found to be associated with thyroid agenesis or dysgenesis." (PMID 26634164, 2015). "Pax-8, Ttf-1, and Ttf-2 are transcription factors crucial to thyroid organogenesis and their absence results in varying degrees of thyroid dysgenesis." (PMID 33806425, 2021). "Additionally, 21.21% (28/132) of mutations were related to thyroid dysgenesis [TSHR (n = 19), TTF1 (n = 5), TTF2 (n = 1), PAX8 (n = 2), and NKX2-5 (n = 1)]." (PMID 30420871, 2018).
brain-lung-thyroid syndrome (3 papers, 2010 to 2021). Brain-lung-thyroid syndrome is a rare disorder characterized by congenital hypothyroidism (CH), infant respiratory distress syndrome (IRDS) and benign hereditary chorea (BHC). "TTF-1 deficiency leads to rare autosomal dominant diseases and brain-lung-thyroid syndrome in humans, such as chorea, hypothyroidism, and infant respiratory distress syndrome." (PMID 34631891, 2021). "Mutations in the TTF-1 gene are associated with "brain-lung-thyroid syndrome" which combines congenital hypothyroidism, neurological symptoms (hypotonia, chorea), and ILD of variable intensity." (PMID 20727133, 2010). "Haploinsufficiency of NKX2.1, the gene encoding the thyroid transcription factor-1 (TTF-1) - critical for lung, thyroid and central nervous system morphogenesis and function - causes a rare form of progressive respiratory failure designated brain-lung-thyroid syndrome." (PMID 21867529, 2011).
carcinoma in situ (3 papers, 2013 to 2022). "Biopsy was consistent with primary SCCB that was poorly differentiated, positive for synaptophysin and chromogranin and TTF-1 and presence of ductal carcinoma in situ component showing neuroendocrine differentiation." (PMID 32411090, 2020). "There were 6 surgical specimens with carcinoma in situ in the periphery of invasive tumors, and 3 of these cases (#2, #4, #6) had TTF-1 expression in the carcinoma in situ component." (PMID 23675755, 2013). "Therefore, although the differences between PMEC and ASC are only minor, PMEC rarely shows an expression of keratinization and in situ carcinoma and a complete absence of TTF-1." (PMID 36385961, 2022).
Chorea (3 papers, 2010 to 2025). Chorea (Greek for 'dance') refers to widespread arrhythmic involuntary movements of a forcible, jerky and restless fashion. "Meanwhile, chorea, with mutations in the TTF-1 gene, was defined as a predominant upper limb movement disorder and improved with age." (PMID 34631891, 2021).
cyst (3 papers, 2013 to 2025). A sac-like closed membranous structure that may be empty or contain fluid or amorphous material. "This study shows that the embryonic airway epithelial cell markers SOX-2 and TTF-1 are retained in the cyst-lining epithelial cells of CPAM human lung tissue." (PMID 32732323, 2020). "TTF-1 staining in cyst-lining epithelium of CPAM lung tissue more closely resembled the generalised epithelial expression of embryonic lung tissue." (PMID 32732323, 2020). "A mucinous cystadenoma, on the other hand, is a true mucin-filled cyst lined by mucous epithelium, with variable expression of TTF-1 antigen." (PMID 23533890, 2013). "If the FNAC had been repeated and combined with an ultrasound of the thyroid and the central lymphatic compartment, as well as HPV-DNA, TTF-1, or a thyroglobulin analysis on the cyst aspirate, the chances of making a correct initial diagnosis had likely increased." (PMID 39962709, 2025). "In CPAM lung tissue sections, all cyst lining epithelial cells stained positively for TTF-1." (PMID 32732323, 2020).
epithelioid mesothelioma (3 papers, 2018 to 2023). "In our first case of epithelioid mesothelioma, the neoplastic cells showed cytokeratin 5/6 (CK5/6), calretinin, and Wilms‐tumor‐1 (WT1) expression, while remaining negative with thyroid transcription factor‐1 (TTF‐1)." (PMID 36808895, 2023).
Follicular adenoma (3 papers, 2012 to 2025). "Follicular adenoma or adenocarcinoma were also ruled out based on negative TTF‐1 immunostaining." (PMID 41320889, 2025).
gastric tumor (3 papers, 2022 to 2026). "The immunohistochemistry results for the gastric tumor were consistent with the lung tumor, also showing positivity for TTF-1, Napsin-A, and CK7, and negativity for CDX2 and CK20." (PMID 39465837, 2024). "Thus, additional TTF-1 immunohistostaining of the gastric tumor biopsy and gastrectomy specimens was performed." (PMID 36459241, 2022).
gastrointestinal carcinoma (3 papers, 2012 to 2013). "Over the past decade, expression levels of CK7, CK20 and TTF-1 have been widely used to distinguish pulmonary from gastrointestinal carcinomas, especially when evaluated as a panel of markers." (PMID 23957943, 2013).
hypothyroidism (3 papers, 2005 to 2011). Abnormally low levels of thyroid hormone. "This pattern differs from the peripheral hypothyroidism typically associated with TTF-1 haploinsufficiency." (PMID 21867529, 2011). "Furterhmore TTF-1 gene variants were found in older children with choreoathetosis, hypothyroidism and respiratory distress." (PMID 15819986, 2005). "In humans, mutations in the TTF-1 gene were associated with chorea, hypothyroidism and respiratory distress in newborns." (PMID 15819986, 2005). "The lack of pituitary TSH results in fetal hypothyroidism, reduced expression of the thyroid hormone inducible transcription factor TTF1 in the lung, and inadequate production of surfactants, known target genes of TTF1." (PMID 22145038, 2011).
lung carcinoid (3 papers, 2018 to 2023). "There were no cases with TTF-1-positive and OTP-negative phenotype in this series; however, we have experienced two recurrent/metastatic lung carcinoid tumors with TTF-1-positive and OTP-negative phenotype, which were not included in this series." (PMID 29770932, 2018). "TTF-1 is usually absent in lung carcinoids but positive in approximately 90% of SCLCs." (PMID 31511024, 2019).
papillary adenocarcinoma (3 papers, 2020 to 2025). A morphologic variant of adenocarcinoma. "The p63/p40 markers were positive in almost all cases (16/18, 88%), with the exception of low-grade papillary adenocarcinoma and one thymic carcinoma with aberrant expression of TTF1 that had been previously published by our group." (PMID 34439210, 2021). "Papillary tumors in the alveoli contain papillary adenoma and papillary adenocarcinoma, which express TTF-1 but do not express the basal cell markers." (PMID 33282636, 2020).
poorly differentiated thyroid carcinoma (3 papers, 2016 to 2025). "Poorly differentiated thyroid carcinoma (PDTC) exhibits diffuse nuclear positivity for thyroid transcription factor 1 (TTF1) and focal positivity for thyroglobulin." (PMID 27213120, 2016).
sellar tumors (3 papers, 2011 to 2025). "This diagnosis is consistent with recent literature describing TTF-1–positive sellar tumors with papillary architecture and no identifiable primary site." (PMID 40664798, 2025).
small bowel tumor (3 papers, 2012 to 2024). "Immunohistochemical analysis demonstrated positivity for Cytokeratin 7 (CK7), Transcription Termination Factor 1 (TTF1) and SWI/SNF-related, matrix-associated, actin-dependent regulator of chromatin, subfamily A, member 4 (SMARCA4) in the metastatic small intestinal tumor." (PMID 39659798, 2024).
subependymal giant cell astrocytoma (3 papers, 2021 to 2025). A benign, slowly growing tumor (WHO grade I) typically arising in the wall of the lateral ventricles and composed of large ganglioid astrocytes. "To check for TTF-1 cross-reactivity, we stained several non-neoplastic tissue and other samples to investigate TTF-1 expression in non-neoplastic CNS tissue and IDH-mutant astrocytomas." (PMID 39899075, 2025).
thyroid adenocarcinomas (3 papers, 2011 to 2023). "Examination of permanent specimens is therefore sometimes necessary for a definitive diagnosis, on immunohistochemical staining, pulmonary and thyroid adenocarcinomas characteristically shows that TTF-1." (PMID 21989021, 2011). "Since DEN can induce lung tumors in mice, we stained lung tumor sections for TTF-1 (thyroid transcription factor-1), a marker of lung and thyroid adenocarcinomas, to distinguish whether these tumors originated from the liver or lung." (PMID 37760565, 2023). "Thyroid transcription factor 1 (TTF-1) was positive in this case of thymic adenocarcinoma, which indicated that a thymic adenocarcinoma with TTF-1-positive may not necessarily be a metastasis of lung or thyroid adenocarcinoma." (PMID 33847622, 2021).
Wilms tumor (3 papers, 2017 to 2020). An embryonal neoplasm characterized by the presence of epithelial, mesenchymal, and blastema components. "The third component was represented by TTF1+/PAX8+ primitive teratoid epithelial tubules reminiscent of primitive thyroid follicles and/or Wilms tumor, admixed with scattered respiratory- or enteric-type tubules, neuroepithelial rosettes, and fetal-type squamoid nests." (PMID 32507920, 2020). "Notably, the Wilms tumor metastasis (post-treatment) contained prominent fibrous stroma entrapping an admixture of native respiratory epithelium as well as minute glands, positive for PAX8, negative with TTF1, indicating neoplastic epithelial origin." (PMID 32193604, 2020).
adenocarcinoma in situ (2 papers, 2017 to 2021). A lesion in which the normally situated glands are partially or completely replaced by atypical cells with malignant characteristics. "In contrast, the tumor cells of the adenocarcinoma and adenocarcinoma in situ were positive for TTF-1 and CK7 but negative for p63." (PMID 34492061, 2021). "Interestingly, the 2011 IASLC/ATS/ERS classification indicated that all the nonmucinous adenocarcinoma in situ (AIS), minimally invasive adenocarcinoma (MIA) and lepidic adenocarcinoma were negative for TTF-1." (PMID 29296178, 2017).
adrenal gland tumor (2 papers, 2013 to 2022). "In our case, melan-A and inhibin were positive, but thyroglobulin and TTF-1 were negative, in the patient’s adrenal gland tumor." (PMID 23889916, 2013).
basaloid carcinoma (2 papers, 2015 to 2024). A malignant epithelial neoplasm characterized by the presence of neoplastic cells with hyperchromatic nuclei, small amount of cytoplasm, and peripheral nuclear palisading. "TTF-1 and 34βE12, associated with the specific neuroendocrine markers, are believed to be helpful panels of antibodies for differentiating basaloid carcinomas from other carcinomas with small cell morphology." (PMID 39268326, 2024). "Approximately 50% of the LCNECs expressed TTF-1, but no basaloid carcinoma expressed TTF-1." (PMID 25452802, 2015).
bronchial carcinomas (2 papers, 2015 to 2017). "The current study aimed at evaluating the utility of a panel of antibodies including TTF-1, P63, HMWK (34βE12), CK7, and cluster of differentiation (CD56) for accurate distinction of bronchogenic carcinomas." (PMID 29531543, 2017). "The current study aimed at evaluating the utility of a panel of antibodies, consisting of thyroid transcription factor (TTF-1), P63, high molecular weight keratin [HMWK (34βE12)], cytokeratin (CK7), and cluster of differentiation (CD56) for accurate distinction of bronchogenic carcinomas." (PMID 29531543, 2017). "TTF-1 staining was performed in four bronchial carcinomas but no expression was found." (PMID 26252375, 2015).
Carcinoid tumours (2 papers, 2009 to 2018). "Carcinoid tumours are typically TTF-1-negative and show positivity with NSE and chromogranin." (PMID 19178730, 2009).
choriocarcinoma (2 papers, 2011 to 2013). An aggressive malignant tumor arising from trophoblastic cells. "We eliminated a choriocarcinoma based on histological examinations, which showed a poorly differentiated carcinoma (AE1-AE3 and CK7 positive, CK20, TTF1 and OCT3-4 negative)." (PMID 24034807, 2013).
choroid plexus carcinoma (2 papers, 2025). A malignant neoplasm arising from the choroid plexus. "Although clone SPT24 is considered to be less specific, because TTF‐1 expression using this clone was rarely found in diffuse gliomas, ependymomas or choroid plexus carcinomas, it displays higher sensitivity than clone 8G7G3/1 in detecting TTF‐1 expression in SEGAs." (PMID 39492623, 2025).
COVID-19 (2 papers, 2020 to 2022). A disease caused by infection with severe acute respiratory syndrome coronavirus 2. "We used dual chromogen immunohistochemistry to stain lung tissue sections of the COVID-19 cases and controls for TTF-1 (brown) and Napsin-A (red) with hematoxylin nuclear counterstain." (PMID 35446789, 2022). "But in COVID-19-affected lung, TTF1 and SFTPC genes were found to be downregulated, whereas SFTPB was upregulated." (PMID 33173052, 2020).